ZP3 (zona pellucida glycoprotein 3)
Description:
Component of the zona pellucida, an extracellular matrix surrounding oocytes which mediates sperm binding, induction of the acrosome reaction and prevents post-fertilization polyspermy. The zona pellucida is composed of 3 to 4 glycoproteins, ZP1, ZP2, ZP3, and ZP4. ZP3 is essential for sperm binding and zona matrix formation.
Synonyms: Zp-3; ZP3A; ZP3B; ZPC; ZP3-424; ZP3-372; OOMD3; OZEMA3
Tractability: Antibody: its Gene Ontology location is reachable by antibodies, with high confidence; UniProt places it where antibodies can reach, with medium confidence; UniProt predicts a signal peptide or a membrane-spanning region. PROTAC: ubiquitination databases record sites on it.
Gene: Protein-coding gene on chromosome 7 (76,397,518 to 76,442,071, forward strand). Ensembl gene ENSG00000188372.
Subcellular location: Zona pellucida (Processed zona pellucida sperm-binding protein 3); Cell membrane
Pathways (Reactome):
Reproduction: Interaction With Cumulus Cells And The Zona Pellucida
Gene Ontology:
Molecular function: acrosin binding; carbohydrate binding; extracellular matrix structural constituent; identical protein binding; protein binding; receptor ligand activity; structural constituent of egg coat
Biological process: binding of sperm to zona pellucida; negative regulation of binding of sperm to zona pellucida; positive regulation of acrosomal vesicle exocytosis; positive regulation of acrosome reaction; positive regulation of humoral immune response; blastocyst formation; egg coat formation; humoral immune response mediated by circulating immunoglobulin; negative regulation of DNA-templated transcription; oocyte development; positive regulation of antral ovarian follicle growth; positive regulation of DNA-templated transcription; positive regulation of inflammatory response; positive regulation of interleukin-4 production; positive regulation of leukocyte migration; positive regulation of ovarian follicle development; positive regulation of T cell proliferation; positive regulation of type II interferon production; positive regulation of type IV hypersensitivity; signal transduction
Cellular component: egg coat; extracellular matrix; extracellular region; plasma membrane
Genetic constraint (gnomAD): Loss-of-function variants: 21 observed, 30.38 expected, observed/expected ratio (o/e) 0.69, 90% interval 0.49 to 1. The upper end of that interval is the gene's LOEUF score, 1, which puts it in group 4 of 6, group 1 being the genes least tolerant of losing a copy. Missense variants: 418 observed, 435.9 expected, observed/expected ratio (o/e) 0.96, 90% interval 0.88 to 1.04. Synonymous variants: 191 observed, 169.15 expected, observed/expected ratio (o/e) 1.13, 90% interval 1 to 1.27.
Homologues: Orthologues: chimpanzee ZP3 (99% identical), macaque ZP3 (93% identical), pig ZP3 (73% identical), dog ZP3 (71% identical), guinea pig Zp3 (69% identical), rabbit ZP3 (69% identical), mouse Zp3 (67% identical), rat Zp3 (66% identical), tropical clawed frog zp3 (41% identical), tropical clawed frog zp3 (39% identical), zebrafish zp3a.2 (29% identical), zebrafish zp3a.1 (29% identical), and 5 more. Paralogues in human: POMZP3 (24% identical).
Diseases named in the same sentence as ZP3 in open-access papers:
ZP3 is named in the same sentence as 38 diseases in open-access papers, as found by Europe PMC text mining. Sharing a sentence is not in itself a finding about the gene and the disease. The quoted sentences say what the papers report.
Infertility (16 papers, 2014 to 2025). "Sixteen primary infertile women with ZP3 mutations were reported in the literature, aged from 26 to 38 years old, with a history of infertility of 2–11 years." (PMID 36476320, 2022). "In conclusion, infertility caused by ZP3 vaccination was mechanistically associated with ovarian OS which triggered depletion of ovarian follicles." (PMID 35252419, 2022). "ZP3 is a principal component of the zona pellucida (ZP) of mammalian oocytes and is essential for normal fertility, and knockout of ZP3 causes complete infertility." (PMID 28145526, 2017). "Mice infected with MCMV expressing murine ZP3 and MCMV expressing ubiquitin tagged ZP3 were 100% infertile." (PMID 37896820, 2023). "Zp3, a critical component of the zona pellucida, plays a vital role in oocyte meiosis and maturation, and knockout of zp3 leads to complete infertility." (PMID 38067041, 2023). "Here we demonstrated that ZP3 vaccination elicited high antibody titers and correlated with reductions of ovarian follicle numbers in both fertile and infertile mice, whereby magnitudes of both factors were negatively correlated with litter size." (PMID 35252419, 2022). "By targeting to block sperm-preferred receptors or enhancing antibody-mediated steric hindrance of sperm, high-titer antibodies produced against ZP3 have been shown to inhibit fertilization, which is a key mechanism of infertility." (PMID 35252419, 2022). "Further, analyses of mutations in the gene encoding human zona proteins from infertile women suggest that ZP1, ZP2, and ZP3 have a role in fertility and assembly of ZP matrix." (PMID 33681199, 2021). "In accordance with infertility in furfl/fl;Zp3-Cre mice, the furfl/fl;Gdf9-Cre female mice were also infertile." (PMID 28569793, 2017). "For example, female mice lacking ZP2 or ZP3 failed to assemble ZP during oocyte growth, which in turn triggered oocyte and ovulation loss, thereby leading to infertility." (PMID 35813655, 2022). "Thus, infertility model resulted from the dominant effect of ZP3-specific antibody-mediated infertility during early stages of immunization and a Non-dominant role of OS at later stages of follicle development together." (PMID 35252419, 2022). "Our work increases the understanding of the pathogenesis of ZP1 and ZP3 gene mutations and recommends selecting a rational fertilization method of ART in combination with ZP target gene diagnosis for infertility patients in the clinic carrying ZP1 mutations and ZP‐free oocytes." (PMID 32573113, 2020). "The normal ovarian functions were interfered with Abs against ZP3 and/or inflammatory cells, which might lead to infertility." (PMID 29751768, 2018). "Recombinant canine ZP3 (cZP3) can also induce infertility in female dogs." (PMID 29751768, 2018). "Dicer Omission bases infertility in females and atypical metaphase spindles in mouse oocyte development, like parent AGO2-zp3-cKO and Dicer-zp3-cKO mice, therefore approving preceding research." (PMID 36564840, 2022). "ZP2-null or ZP3-null mice produced eggs without a ZP, as well as infertility." (PMID 36476320, 2022). "Furthermore, the total number of follicles was comparable in adult Smc3fl/fl, Smc3fl/fl;Gdf9-iCre and Smc3fl/fl;Zp3-Cre female mice, suggesting that differences in ovarian reserve do not account for infertility." (PMID 34935904, 2021). "Moreover, the CL is the collapsed structure of the follicular wall remaining in the ovary after ovulation, is closely related to the ovulation cycle of the female individual, and both increased significantly in the SS-treated and ZP3-immunized mice without SS treatment, especially the infertile one." (PMID 35252419, 2022).
female infertility (12 papers, 2018 to 2025). Diminished or absent ability of a female to achieve conception. "The oocyte-specific ablation of Lonp using Gdf9-cre or Zp3-cre results in female infertility due to impaired follicle development, loss of the ovarian reserve, and progressive oocyte death (." (PMID 40558552, 2025). "The introduction of the same mutation at later oocyte development by using Zp3-cre also resulted in female infertility but because of failure in preimplantation development." (PMID 35600599, 2022). "In the literature, ZP1, ZP2, and ZP3 gene alterations have been associated with female infertility, mainly on the grounds of ZP defects." (PMID 34501995, 2021). "Together, these findings suggested that disruption of furin‐mediated cleavage of ZP2 impairs ZP formation and perturbs the proper localization of ZP1 and ZP3, ultimately leading to female infertility consistent with EFS." (PMID 41394961, 2025). "The conditional ablation of Furin using Gdf9-cre or Zp3-cre leads to female infertility due to arrested folliculogenesis at the secondary follicle stage." (PMID 40558552, 2025). "ZP3 knockout mice and human genetic mutation in this gene (OMIM:617712) have been shown to exhibit female infertility due to zona pellucida defect." (PMID 39702772, 2024). "Conditional ablation of Furin by Gdf9-cre or Zp3-cre; Furinfl/fl result in female infertility because of the arrested oogenesis at early secondary follicles." (PMID 35600599, 2022). "Oocyte-specific Lonp ablation by Gdf9-cre or Zp3-cre; Lonp1fl/fl results in female infertility because of impaired follicular development, progressive oocyte death, ovarian reserve loss." (PMID 35600599, 2022). "With regards to female germ cell development, a previous study reported that deletion of CDC42 in activated oocytes via follicle-specific Zp3-Cre disrupts oocyte maturation and leads to complete female infertility." (PMID 29976179, 2018). "Here, using mouse models with disrupted furin cleavage sites in ZP1, ZP2, and ZP3, we found that loss of the furin site in ZP2 caused female infertility associated with empty follicle syndrome (EFS), manifested by the failure to retrieve oocytes after ovarian hyperstimulation." (PMID 41394961, 2025). "Based on female infertility with both Gdf9-iCre and Zp3-Cre drivers and by scoring the number of follicles in ovaries, we investigated whether loss of Smc3 impacts ovarian reserve." (PMID 34935904, 2021). "Previous studies have reported that mutations in human ZP1, ZP2 and ZP3 influence their functions and result in a lack of ZP or in an abnormal oocytes and empty follicle syndrome, which leads to female infertility." (PMID 32573113, 2020). "Studies have reported that the variants in ZP1(MIM: 195000), ZP2 (MIM: 182888), and ZP3 (MIM: 182889) affect the formation of zona pellucida and result in female infertility, but there is no convincing evidence to prove that ZP4 (MIM: 613514) variant responsible for female infertility." (PMID 37052235, 2023). "Intact primordial, primary, secondary, and antral follicles were all observed in Rnf20Flox/Flox and Zp3‐Rnf20−/− ovaries, which suggests that female infertility may not be caused by the failure of follicular development but rather by defective oocyte meiotic maturation." (PMID 38240347, 2024).
empty follicle syndrome (8 papers, 2020 to 2025). "A different but related example of dominant‐negative mutation is represented by recently described human ZP3 A134T, which causes female sterility due to empty follicle syndrome and affects a residue at the N‐terminal end of ZP‐N βG." (PMID 33196145, 2020). "Moreover, mutations in ZP1, ZP2, and ZP3 genes have been associated with empty follicle syndrome (EFS), marked by the absence of oocytes within follicles, highlighting the essential roles of ZP proteins not only in fertilization but also in folliculogenesis." (PMID 41394961, 2025).
ovarian carcinoma (2 papers, 2022 to 2023). A malignant neoplasm originating from the surface ovarian epithelium. "ZP3 protein was abundantly expressed in granulosa cell tumors, a rare form of ovarian cancer, and was unexpectedly shown to localize to the cytoplasm, contradicting the plasma membrane localization and extracellular secretion of ZP3 in oocytes." (PMID 38125942, 2023). "Cytoplasmic expression of the ZP3 protein in cancer has been shown before in ovarian granulosa cell tumors, a rare form of ovarian cancer." (PMID 38125942, 2023). "A treatment strategy in mice for ovarian cancer that is based upon immunization against murine ZP3 has also been published." (PMID 35330493, 2022). "However, in mice, ZP3 has been used as treatment approach against ovarian cancer based upon immunization against murine ZP3." (PMID 35330493, 2022).
ovarian dysfunction (2 papers, 2022 to 2024). The inability of the ovaries to function. "Although individual differences are observed among experimental subjects, ZP3-induced ovarian inflammation is closely associated with ovarian dysfunction and fertility, with severe inflammation often accompanied with fewer follicles and smaller litter sizes." (PMID 35252419, 2022).
prostate carcinoma (2 papers, 2021 to 2023). A carcinoma that arises from epithelial cells of the prostate gland. "Another study showed ZP3 protein localization to the cytoplasm of the human prostate cancer cell line PC3, but there also appeared to be ZP3 staining at the cell membrane." (PMID 38125942, 2023). "Also in the prostate cancer cell line PC3, ZP3 protein appeared dominantly cytoplasmic." (PMID 38125942, 2023). "Inter alia, Costa and colleagues have demonstrated that ZP1, ZP3, and ZP2, but not ZP2-specific transcripts, are expressed in prostate cancer-derived PC3 cells and prostate tumor tissue." (PMID 33917056, 2021).
renal clear cell carcinoma (2 papers, 2022 to 2023). "A recent publication deals with ZP3 as new prognostic and potential therapeutic marker in renal clear cell carcinoma showing ZP3 30-fold higher expressed in tumor versus normal counterparts." (PMID 35330493, 2022). "An earlier study focusing on prognostic markers for renal clear cell carcinoma (KIRC; TCGA cohort) revealed significant correlations between ZP3 expression level and OS, DSS and progression-free survival." (PMID 38125942, 2023).
sterility (2 papers, 2019 to 2020). "In an MCMV-based immunocontraception setting to prevent mouse plagues, the expression of the zona pellucida 3 (ZP3), a self-antigen from the egg and a primary sperm receptor, induced sterility in mice." (PMID 31627457, 2019).
autoimmune (1 paper, 2025). "In autoimmune POI models (for example, IFN-γ injury and ZP3 immunization), aberrant NF-κB signaling primes NLRP3–caspase-1–GSDMD-mediated granulosa-cell pyroptosis." (PMID 41465179, 2025).
breast carcinoma (1 paper, 2023). "ZP3 protein was detected in lung squamous cell carcinoma, ovarian adenocarcinoma, breast carcinoma and esophageal adenocarcinoma." (PMID 38125942, 2023).
colon cancer (1 paper, 2021). "In contrast, ZP1, ZP3, and ZP4 were not detectable at all or only in a small number of colon cancer specimens." (PMID 33917056, 2021).
lung squamous cell carcinoma (1 paper, 2023). "For patients with prostate adenocarcinoma (PRAD), triple-negative breast cancer (BRCA-TNBC) and lung squamous cell carcinoma (LUSC), at least 50% of tumors display medium to high ZP3-Cancer expression levels." (PMID 38125942, 2023).
Obesity (1 paper, 2024). Accumulation of substantial excess body fat. "Human females with missense mutations in the ZP3 gene are infertile thus altered ZP3 due to obesity might compromise female fertility." (PMID 38813940, 2024).
osteosarcoma (1 paper, 2020). A usually aggressive malignant bone-forming mesenchymal neoplasm, predominantly affecting adolescents and young adults. "Furthermore, AMN1 and ZP3 may be protective factors in osteosarcoma (HR: 1.26e−36 and 1.13e−07, respectively), whereas LIMS1, SAMD4A, and SPARC appear to be harmful factors in this setting (HR: 699.2, 167, and 298.7, respectively)." (PMID 33195283, 2020). "Although there are no relative studies about the role of ZP3 in osteosarcoma, even if in cancer, combined with the findings of our study, we should also pay attention to AMN1 and ZP3 in osteosarcoma in a certain extent." (PMID 33195283, 2020).
Premature ovarian insufficiency (1 paper, 2020). Amenorrhea due to loss of ovarian function before the age of 40. "By establishing an inducible premature ovarian insufficiency (POI) mouse model through selectively ablating growing follicles in Zp3‐Cre;iDTR mice, we further revealed that our in vivo EGF treatment system improved primordial follicle activation and ovulation of POI ovaries significantly." (PMID 32997412, 2020).
serous ovarian cancer (1 paper, 2023). "In that study, intracellular ZP3 protein was also detected in the human serous ovarian cancer derived cell line OVCAR3." (PMID 38125942, 2023).
cancer (4 papers, 2018 to 2023). A tumor composed of atypical neoplastic, often pleomorphic cells that invade other tissues. "Higher levels of the ZP3-Cancer transcript were associated with more aggressive tumors and worse survival of patients with various types of cancer." (PMID 38125942, 2023). "An initial interrogation of its oncological properties suggests ZP3-Cancer is associated with more aggressive behavior of tumor cells and may confer a survival advantage to these cells when expressed at higher levels." (PMID 38125942, 2023). "This novel transcript, which we termed ZP3-Cancer, lacks the genetic information encoding the N-terminal signal peptide, which, in oocytes, governs entry of the ZP3 protein into the secretory pathway, anchoring into the plasma membrane and eventually extracellular release into the ZP layer." (PMID 38125942, 2023). "In addition, an increased ZP3-Cancer expression level was statistically significantly associated with poorer outcome for all four distinct clinical survival parameters in KIRC and UCEC, and three of the four in BLCA." (PMID 38125942, 2023). "ZP3-Cancer appeared highly significantly enriched in numerous cancer types as compared to the respective healthy tissues (p < 0.0001), but also to healthy tissues in general." (PMID 38125942, 2023). "To support its validity as therapeutic target, we extended the cancer related data by investigating ZP3 expression using immunohistochemistry (IHC) of tumor biopsies." (PMID 38125942, 2023). "Ectopic expression of ZP3 has been observed in various types of cancer, rendering it a possible therapeutic target." (PMID 38125942, 2023). "Our findings pinpoint ZP3-Cancer as a strongly cancer-enriched antigen, which provides a promising window for an immunotherapy-based intervention employing its unique mRNA sequence." (PMID 38125942, 2023). "To expand the picture of cancer related expression and cellular localization of ZP3, we performed IHC for a number of tumor tissues obtained from patients with different types of cancer." (PMID 38125942, 2023). "Cell-based phenotypic and genetic perturbation studies are needed to characterize the oncological properties of ZP3-Cancer in more detail." (PMID 38125942, 2023). "ZP3-Cancer transcript levels appear enriched in solid tissue type cancers, while those originating in the brain or are blood cell derived generally show low(er) expression levels." (PMID 38125942, 2023). "Cancer-enriched expression of ZP3 has been shown before (also a comparison of TCGA tumors and GTEx healthy tissues), although those findings related to ZP3 gene-level expression analysis (expression levels of all seven ZP3 transcripts combined)." (PMID 38125942, 2023). "The cancer-restricted expression of ZP3-Cancer renders it an attractive tumor antigen for the development of a therapeutic cancer vaccine, particularly using mRNA expression technologies." (PMID 38125942, 2023). "Overall, the data show that ZP3-Cancer expression is enriched in cancer, and that its expression level varies considerably among the different cancer types." (PMID 38125942, 2023). "To obtain a first glimpse of the oncological character of ZP3-Cancer, we investigated a relationship between its expression level and pathological and clinical parameters." (PMID 38125942, 2023). "Our data show that ZP3-Cancer is expressed at varying levels in cancer (sub)types, but also that it is highly enriched in tumor tissues as compared to healthy tissues, where it is virtually absent." (PMID 38125942, 2023). "From a total of 1816 genes classified as secretory, a core set of 16 genes, which included ZP3, was identified of which the RNA expression was increased in most of the cancer types as compared to normal tissues." (PMID 38125942, 2023). "The ZP3-Cancer transcript was detected in both MCF7 and HeLa cells, and at much higher levels compared to the ZP3-Oocyte transcript, corroborating the RNAseq data." (PMID 38125942, 2023).